PML (PML nuclear body scaffold)
Diseases named in the same sentence as PML in open-access papers (continued):
Sharing a sentence is not in itself a finding about the gene and the disease.
acute promyelocytic leukemia (continued). "Arsenic trioxide (ATO) is able to selectively target and degrade the disease-causing PML::RARα (P/R) oncoprotein in acute promyelocytic leukemia (APL) for curing the disease." (PMID 40330660, 2025). "Acute myeloid leukemia with NPM1, IDH2, and SETD2 mutations can mimic acute promyelocytic leukemia (APL) and poses a challenge for the early and accurate differentiation and diagnosis of APL with PML::RARA." (PMID 39432585, 2024). "The hallmark of acute promyelocytic leukemia (APL) is the presence of the characteristic fusion transcript of the promyelocytic leukemia gene with the retinoic acid receptor α gene (PML::RARA)." (PMID 38539495, 2024). "The identification of several gene mutations can guide treatment, such as PML-RARA for acute promyelocytic leukemia (APL)." (PMID 35898936, 2022). "Acute promyelocytic leukemia (APL) is a unique subtype of acute myeloid leukemia (AML) that is characterized by the PML::RARA fusion or, more rarely, a variant RARA translocation." (PMID 36672788, 2022). "PML was originally found in patients who have acute promyelocytic leukemia (APL), which is caused by the fusion of PML with the retinoic acid receptor alpha (RARA) gene, which results in the expression of a chimeric protein PML-RARα." (PMID 34930370, 2021). "PML–RARα is a transcription factor which underlies the pathogenesis of acute promyelocytic leukemia (APL)." (PMID 34298959, 2021). "Most acute promyelocytic leukemia (APL) are caused by PML-RARA, a translocation-driven fusion oncoprotein discovered three decades ago." (PMID 32295268, 2020). "Notably, many of these host factors have been shown to either reside or transiently associate with promyelocytic leukaemia nuclear bodies (PML-NBs, also known as ND10;), which rapidly associate with and entrap infecting viral DNA (vDNA) as a component of the intrinsic antiviral immune response." (PMID 30901352, 2019). "During the development of acute promyelocytic leukemia (APL), the PML-RARα fusion protein has been demonstrated to underlie the abnormal transcription and the consequent rapid growth of tumor cells." (PMID 26510911, 2015). "In acute promyelocytic leukemia (APL), a chromosomal translocation between the PML gene and the gene encoding the retinoic acid receptor alpha (RARα) results in the formation of a PML-RARα fusion protein that is responsible for the disease." (PMID 24656128, 2014). "In accordance with the two-hit hypothesis of leukemic transformation, FLT3-ITD expression in mouse bone marrow cells expressing a promyelocytic leukemia (PML)/retinoic acid receptor (RAR) α fusion protein of acute promyelocytic leukemia (APL) caused accelerated malignant transformation." (PMID 21453545, 2011). "This fused PML-RARA oncogene is associated with acute promyelocytic leukemia (APL) and is responsible for increasing the expression of key cancer proteins in APL." (PMID 20815877, 2010). "Background and Clinical Significance: Acute promyelocytic leukemia (APL) is a rapidly progressive subtype of acute myeloid leukemia defined by PML::RARA fusion and characterized by life-threatening coagulopathy." (PMID 41718414, 2026). "The ability to chemically synthesize RNF4 will enable future studies of its structure and biological function, particularly its role in degrading the oncoprotein PML-RARα in acute promyelocytic leukemia." (PMID 41636446, 2026). "Mechanistically, the epigenetic readers like bromodomain-containing protein 4-dependent (BRD4-dependent) super enhancers (SEs) activate proinflammatory genes, including promyelocytic leukemia (PML)." (PMID 41842990, 2026). "It represents the structural core of promyelocytic leukemia nuclear bodies (PML-NBs), which are dynamic, membrane-less nuclear domains involved in the regulation of essential cellular processes." (PMID 41440764, 2025).
acute promyelocytic leukemia (continued). "In promyelocytic leukemia nuclear bodies (PML NBs), phosphorylation of Daxx’s SIM enhances its binding to SUMOylated PML, leading to the sequestration and inactivation of Daxx within PML NBs." (PMID 40724953, 2025). "Previous studies have shown that the major and minor capsid proteins accumulate at discrete intranuclear sites known as promyelocytic leukemia nuclear bodies (PML-NBs), where virus-like particles (VLPs) are formed." (PMID 41157668, 2025). "Most cases of acute promyelocytic leukemia (APL) are driven by the PML::RARA fusion gene, which is sensitive to differentiation induction therapy comprising of all-trans retinoic acid (ATRA) and arsenic trioxide (ATO)." (PMID 40386562, 2025). "After evaluating the biocompatibility of resin BV007a, we wanted to transfer the microfluidic detection of PML::RARA for the diagnosis of acute promyelocytic leukemia to 3D-printed microfluidic chips made of BV007a." (PMID 39859217, 2025). "The MND pattern characteristic of PBC is associated with antibodies directed against structural components of the nuclear proteins of promyelocytic leukemia—PML NB such as Sp100, PML, and Sp140." (PMID 40005074, 2025). "Previously, in cell culture systems, we demonstrated that these capsid proteins accumulate in intranuclear domains known as promyelocytic leukemia nuclear bodies (PML-NBs), where they assemble into virus-like particles (VLPs)." (PMID 41157668, 2025). "Arsenic trioxide, for instance, promotes SUMO1/2 chain formation on PML-RARα, inducing its degradation and differentiation of promyelocytic leukemia cells, and is now a standard therapy for acute promyelocytic leukemia (APL)." (PMID 41268439, 2025). "In another study, promyelocytic leukemia (PML), ATO showed high binding affinity to cysteine residues, resulting in the initiation of PML/RARα (retinoic acid receptor α) gene degradation." (PMID 41154495, 2025). "Despite the high efficacy of all-trans retinoic acid (ATRA) and arsenic trioxide (ATO) in treating acute promyelocytic leukemia (APL), approximately 10-20% of patients develop drug resistance due to mutations in PML-RARα and other factors." (PMID 41445506, 2025). "Among them, three patients with M3 (acute promyelocytic leukemia) were detected with PML/RARA fusion genes, and four patients showed multiple chromosomal structure and quantity abnormalities." (PMID 40028267, 2025). "Three cases of M3 were positive for promyelocytic leukemia and Vitamin A acid receptor alpha (PML/RARA) fusion genes, and four patients presented multiple chromosome structure and number abnormalities." (PMID 40028267, 2025). "qPCR is the oldest method for molecular MRD, and has been used to follow PML::RARA fusion transcripts in acute promyelocytic leukemia since as early as the 1990s." (PMID 38396825, 2024). "This group encompasses acute promyelocytic leukemia (APL) with PML::RARA fusion, which is distinct due to its responsiveness to targeted therapy with all-trans retinoic acid (ATRA) and arsenic trioxide." (PMID 39538363, 2024). "Examples of MLO encompass the nuclear kernel, P granules, stress granules (SGs), Promyelocytic Leukemia (PML) bodies, and nuclear granules." (PMID 38383403, 2024). "Both HIT and APL were confirmed with serotonin release assay (SRA) and promyelocytic leukemia/retinoic acid receptor alpha (PML-RARA) fusion assay, respectively." (PMID 38800206, 2024). "The M3 group, also called “acute promyelocytic leukemia”, and which represents a separate entity characterized by the PML-RARA chromosomal translocation, shows a homogenous pattern of AKT3 expression, and a significant ~ twofold increase in AKT2 expression." (PMID 38528080, 2024). "In contrast to these studies of NE-regulated suppression of cancer, ELANE is expressed in promyelocytic leukemia (PML) and sustains PML by inhibiting apoptosis via degradation of BAX a pro-apoptotic protein and upregulation of Bcl-2, an apoptosis inhibitor." (PMID 39684750, 2024).
acute promyelocytic leukemia (continued). "Promyelocytic leukemia/retinoic acid receptor alpha (PML/RARA) gene translocation DNA probe revealed a fusion of PML and RARA loci in 2 of 100 interphase nuclei, confirming the anomaly in chromosome studies." (PMID 39050334, 2024). "In the G2M Checkpoint hallmark, genes such as B-Cell Lymphoma 3 (BCL3), Cyclin C (CCNC), and Promyelocytic Leukemia (PML) are downregulated under Fe ion irradiation conditions compared to photon irradiation conditions." (PMID 39286254, 2024). "Arsenic trioxide (As2O3) is a therapeutic drug used for the treatment of acute promyelocytic leukemia (APL) by promoting degradation of the PML–retinoic acid receptor-α (PML-RAR) oncogene." (PMID 38752489, 2024). "WHO 2022 has eliminated the requirement of a ≥20% blast count as a diagnostic cut-off should a defining genetic abnormality such as PML/RARA in acute promyelocytic leukemia (APL) and core-binding factor AML (e.g., RUNX1-RUNX1T1, CBFB-MYH11) be present." (PMID 39199685, 2024). "This notion was verified by assessing colocalization of the viral DNA (vDNA) and promyelocytic leukemia nuclear bodies (PML NBs)." (PMID 38370412, 2024). "The successful reprogramming of cancer cells into differentiated cells has been implemented before, most notably in PML-RARα fusion-driven acute promyelocytic leukemia." (PMID 39030166, 2024). "The therapeutic efficacy of ATO is attributed to its induced degradation effect of the promyelocytic leukemia–retinoic acid receptor α (PML-RARA) oncogenic fusion protein, thereby relieving the block in myeloid differentiation of leukemic cells." (PMID 38165043, 2024). "Molecular examination revealed promyelocytic leukemia (PML)-retinoic acid receptor alpha (RARα) fusion protein by reverse-transcription polymerase chain reaction (RT-PCR)." (PMID 39483936, 2024). "The successful reprogramming of cancer cells into differentiated cells has been implemented in other malignancies, most notably PML-RARα fusion-driven acute promyelocytic leukemia." (PMID 39030166, 2024). "Acute promyelocytic leukemia (APL) is a subtype of acute myeloid leukemia defined by a fusion gene transcript called PML::RARA." (PMID 39589180, 2024). "In principle, this is exemplified when ATRA is used to treat acute promyelocytic leukemia (PML) and target RARα within PML-RARα oncogenic fusion protein." (PMID 38928275, 2024). "With this method, the authors revealed the role of SUMOylation in promyelocytic leukemia nuclear bodies (PML NBs) in early promyelocytic leukemia (PML) and discovered 59 SUMO-dependent PML-interacting proteins." (PMID 37777761, 2023). "A landmark clinical study reported that ATRA leads to the eradication of acute promyelocytic leukemia-initiating cells by the degradation of PML-RARα fusion protein." (PMID 37686465, 2023). "Further study found that the interaction between hypertriglyceridemia and acute promyelocytic leukemia is mediated by the cooperation of peroxisome proliferator-activated receptor-alpha with PML/RAR alpha fusion protein on the super enhancer." (PMID 37441519, 2023). "During the development of acute promyelocytic leukemia (APL), the aberrant phase separation of PML/RARα caused by neddylation of the RARα moiety results in the failure of PML nuclear body (NB) assembly, which is essential for tumor suppression." (PMID 37299568, 2023). "Similar to promyelocytic leukemia-retinoic acid receptor α (PML-RARA) rearrangement, NPM1 can also serve as a marker for the surveillance of minimal residual disease (MRD) in AML patients." (PMID 36824144, 2023).
acute promyelocytic leukemia (continued). "In some AML subsets, oncogenic drivers impose a block of differentiation by directly perturbing the expression of lineage commitment genes, as is the case of the PML‐RARα fusion protein of acute promyelocytic leukemia (APL)." (PMID 37807875, 2023). "The suppression of PHRF1 activity by PML-RARα facilitates the progression of acute promyelocytic leukemia (APL)." (PMID 37540725, 2023). "Arsenic trioxide (ATO, also known as Trisenox) is an FDA-approved drug to treat acute promyelocytic leukemia (APL) that is characterized by the expression of PML-RARα fusion protein." (PMID 36672377, 2023). "Promyelocytic leukemia nuclear bodies (PM NBs), often referred to as membraneless organelles, are dynamic macromolecular protein complexes composed of a PML protein core and other transient or permanent components." (PMID 37127643, 2023). "This agent also induced differentiation of human acute promyelocytic leukemia cells and clearance of murine malignant PML-RARα+ cells in vivo." (PMID 37686465, 2023). "Acute promyelocytic leukemia (APL), a hematological malignancy caused by PML—RARα could be successfully treated by all-trans retinoic acid and trivalent arsenic." (PMID 37686409, 2023). "This targets the PML element of PML-RARα, ultimately leading to apoptosis of acute promyelocytic leukemia cells." (PMID 37915415, 2023). "Our results have revealed PML as a common factor connecting pediatric gliomas and promyelocytic leukemias." (PMID 38066546, 2023). "As a curative frontline treatment for APL, ATO-ATRA molecularly targets the oncogenic fusion protein; promyelocytic leukaemia–retinoic acid receptor α (PML::RARA)." (PMID 36834572, 2023). "The PML gene was named for its role in a subtype of myeloid leukemias called acute promyelocytic leukemia (APL)." (PMID 38066546, 2023). "Other substrates of E6AP such as the polycomb protein Ring1B and PML (promyelocytic leukemia) tumour suppressor were also reported previously to modulate proliferation-differentiation balance." (PMID 37379354, 2023). "Promyelocytic leukemia nuclear bodies (PML-NBs) are multiprotein complexes with an average size of 0.2 to 1.0 μm." (PMID 35699431, 2022). "Promyelocytic leukemia (PML) nuclear bodies (PML-NBs), a class of membrane-less cellular organelles, participate in various biological activities." (PMID 35579421, 2022). "This has been achieved for most cases of acute promyelocytic leukemia which is driven by the leukemia fusion protein PML-RARα." (PMID 34665271, 2022). "SP100 is a type of nuclear antigen which encodes a subnuclear organelle and is major component of the PML- (promyelocytic leukemia-) SP100 nuclear bodies." (PMID 35971449, 2022). "This is in contrast to acute promyelocytic leukemia, in which the presence of very low amounts of PML-RAR positive cells after therapy almost invariably leads to relapse of the disease." (PMID 35024892, 2022). "PML derived its name due to the discovery that over 90% of patients with acute promyelocytic leukemia (APL) harbor a chromosomal translocation, which joins the PML gene with the gene encoding the retinoic acid receptor alpha (RARα)." (PMID 36230470, 2022). "We first showed a dose-dependent effect of ATO in vitro on human promyelocytic leukemia (PML) cell line (HL-60) viability and H2O2 and GSH production." (PMID 36016953, 2022). "PML is known as the key organizer of the PML-Nuclear Bodies (PML-NBs), and has fascinated scientists for many years due to its multifaceted role under many cellular conditions, notably acute promyelocytic leukemia." (PMID 35406736, 2022). "This block in differentiation was associated with a gene expression signature that was enriched for genes responsive to treatment with ATRA, analogous to promyelocytic leukemia/retinoic acid receptor α (PML/RARα)-driven APL." (PMID 34967233, 2022).
acute promyelocytic leukemia (continued). "In acute promyelocytic leukemia, it is required for the degradation of the fusion oncoprotein PML-RARα, resulting in the differentiation of the leukemic cells." (PMID 36153321, 2022). "The encoded PML-RARA protein serves as a driving event of acute promyelocytic leukemia (APL)." (PMID 36384590, 2022). "Arsenic trioxide (ATO) plus all-trans retinoic acid (ATRA) had been proved a successful strategy in acute promyelocytic leukemia (APL), a unique AML subtype characterized by the fusion protein of promyelocytic leukemia (PML)–retinoic acid receptor ɑ (RARɑ)." (PMID 36237321, 2022). "PML/RARα-regulated miR-181a/b cluster targets the tumor suppressor RASSF1A in acute promyelocytic leukemia." (PMID 35366954, 2022). "According to FAB classification, AML-M3 is a subtype of AML characterized by the presence of promyelocytic leukemia-retinoic acid receptor alpha (PML-RARA) genes fusion." (PMID 36144542, 2022). "In acute promyelocytic leukemia, the fusion protein PML-RARA disrupts the PML body’s function, promoting transformation." (PMID 35406602, 2022). "Promyelocytic leukemia nuclear bodies (PML-NBs) were considered to maintain antiviral capacity, as these spherical complexes are antagonized by viruses." (PMID 35699431, 2022). "PML-RARA is a well characterized fusion gene in acute promyelocytic leukemia (APL), which is a clinically and biologically unique subtype of AML." (PMID 35251131, 2022). "The presence of Auer rods in neutrophils and monocytes are rarely reported, most commonly in association with acute promyelocytic leukemia (APL) with PML‐RARA and AML with RUNX1‐RUNX1T1, occasionally seen in other subtypes of AML and myelodysplastic syndrome (MDS) in the literature as well." (PMID 36051019, 2022). "Even though most of the snoRNAs appeared to be downregulated, the study showed that a cluster of snoRNAs located at the DLK1-DIO3 locus was overexpressed in samples of acute promyelocytic leukemia (APL) carrying the PML-RARalpha_bcr1 translocation." (PMID 34842767, 2021). "Previous studies have primarily focused on the retinoic acid signaling pathway and how it is interfered with by promyelocytic leukemia/retinoic acid receptor-α (PML/RARα) fusion protein." (PMID 33901013, 2021). "Dnmt3A is required for PML–RARA to initiate acute promyelocytic leukemia, as it is needed for PML–RARA to drive the aberrant self-renewal of mouse bone marrow cells ex vivo." (PMID 34575830, 2021). "Meanwhile, RNF4 acts as a tumor suppressor in promyelocytic leukemia (PML) through the degradation of an oncogenic fusion protein between PML protein and retinoic acid receptor α." (PMID 34071450, 2021). "Promyelocytic leukemia nuclear bodies (PML NBs) are multi-protein assemblies representing distinct sub-nuclear structures." (PMID 34513832, 2021). "Deregulated HDAC3 acts as a crucial role in the progress of acute promyelocytic leukemia (APL) with PML-RARα fusion protein." (PMID 34540702, 2021). "Concerning the restriction phenotype of Mre11, formation of protein complexes known to restrict HSV-1 replication, termed PML (promyelocytic leukemia) nuclear bodies (PML-NBs) or nuclear domain 10 bodies, is sensitive to Mre11 depletion." (PMID 33563816, 2021). "They found that a small percentage of cases remained, and these were categorized under AML M3 as per FAB classification, which is now categorized as acute promyelocytic leukemia (APL) with PML/RARA under AML-RGA." (PMID 33973643, 2021). "The study showed a decrease in the HOTAIRM1 expression in APL (acute promyelocytic leukemia) leading to the inhibition of all-trans-retinoic acid (ATRA) mediated degradation of PML-RARA causes repression of promyelocytic to granulocytic cellular differentiation." (PMID 34303380, 2021).